ITIH1 (inter-alpha-trypsin inhibitor heavy chain 1)
Description:
May act as a carrier of hyaluronan in serum or as a binding protein between hyaluronan and other matrix protein, including those on cell surfaces in tissues to regulate the localization, synthesis and degradation of hyaluronan which are essential to cells undergoing biological processes. Contains a potential peptide which could stimulate a broad spectrum of phagocytotic cells.
Synonyms: ITI-HC1; SHAP; H1P; IATIH; ITIH
Tractability: Antibody: UniProt places it where antibodies can reach, with medium confidence; UniProt predicts a signal peptide or a membrane-spanning region; its Gene Ontology location is reachable by antibodies, with medium confidence. PROTAC: its protein half-life has been measured.
Gene: Protein-coding gene on chromosome 3 (52,777,567 to 52,792,068, forward strand). Ensembl gene ENSG00000055957.
Subcellular location: Secreted
Subcellular location (Human Protein Atlas): Vesicles; Predicted to be secreted
Gene Ontology:
Molecular function: carbohydrate binding; hyaluronic acid binding; protein binding; calcium ion binding; serine-type endopeptidase inhibitor activity
Biological process: hyaluronan metabolic process
Cellular component: blood microparticle; extracellular exosome; extracellular matrix; extracellular region
Genetic constraint (gnomAD): Loss-of-function variants: 91 observed, 101.36 expected, observed/expected ratio (o/e) 0.9, 90% interval 0.76 to 1.07. The upper end of that interval is the gene's LOEUF score, 1.07, which puts it in group 4 of 6, group 1 being the genes least tolerant of losing a copy. Missense variants: 1,187 observed, 1,205.1 expected, observed/expected ratio (o/e) 0.98, 90% interval 0.94 to 1.03. Synonymous variants: 453 observed, 477.52 expected, observed/expected ratio (o/e) 0.95, 90% interval 0.88 to 1.02.
Homologues: Orthologues: chimpanzee ITIH1 (98% identical), macaque ITIH1 (97% identical), guinea pig ITIH1 (83% identical), rabbit ITIH1 (83% identical), dog ITIH1 (83% identical), pig ITIH1 (82% identical), mouse Itih1 (82% identical), rat Itih1 (80% identical). Paralogues in human: ITIH3 (53% identical), ITIH2 (37% identical), ITIH4 (34% identical), ITIH5 (30% identical), ITIH6 (30% identical), PARP4 (16% identical), VWA3B (16% identical), VWA3A (15% identical), VWA5A (14% identical), VWA5B1 (14% identical), VWA5B2 (12% identical).
Diseases named in the same sentence as ITIH1 in open-access papers:
ITIH1 is named in the same sentence as 61 diseases in open-access papers, as found by Europe PMC text mining. Sharing a sentence is not in itself a finding about the gene and the disease. The quoted sentences say what the papers report.
COVID-19 (5 papers, 2021 to 2022). A disease caused by infection with severe acute respiratory syndrome coronavirus 2. "Previously, it was reported that ITIH1 and ITIH2 were more abundant in a COVID-19 survivor group." (PMID 36131342, 2022).
hepatocellular carcinoma (5 papers, 2015 to 2025). A malignant tumor that arises from hepatocytes. "ITIH2 mRNA is downregulated in multiple solid tumors, while ITIH1 mRNA undergoes downregulation in hepatocellular carcinoma." (PMID 40178908, 2025). "Both ITIH1 and ITIH3 encode one heavy chain of inter-alpha-trypsin inhibitor (ITI), which is one plasma protease inhibitor, and is synthesized and secreted in a hepatoma HepG2 cell culture and COS7 cell culture." (PMID 25946105, 2015).
bipolar disorder (4 papers, 2014 to 2025). A disorder of the brain that causes unusual shifts in mood, energy, activity levels and the ability to carry out day-to-day tasks. "One example is the inter-alpha-trypsin inhibitor heavy chain gene family (ITIH1, ITIH3, ITIH4), which has been associated with major psychiatric disorders including MDD, bipolar disorder and schizophrenia." (PMID 30626913, 2020). "The result showed that 6 genes (including MAD1L1, JAM3, MYL12B, MYL12A, ITIH1 and RYR2) had been reported to be significant associated with bipolar disorder in at least one genetic study." (PMID 26193471, 2015). "Some research suggested that ITIH1 may be related to the incidence of Bipolar disorder and human solid tumors." (PMID 24433274, 2014).
Insulin resistance (4 papers, 2020 to 2024). Increased resistance towards insulin, that is, diminished effectiveness of insulin in reducing blood glucose levels. "Interestingly, the genes with the second and third highest FC in this study, namely IGFBP1 (log2FC = 11.29) and ITIH1 (log2FC = 11.20), respectively, were also associated with insulin resistance." (PMID 37889672, 2023). "Further, increased liver expression of ITIH1 has been correlated with markers of insulin resistance and diabetes in humans, and serum levels were associated with diabetic retinopathy in prior studies in a small cohort." (PMID 39316441, 2024). "Glycosyl modification of ITIH1 has been shown to produce a physical barrier between insulin receptors and circulating insulin, exacerbating insulin resistance and subsequently increasing inflammation." (PMID 32933222, 2020). "Inter-alpha-trypsin inhibitor heavy chain H1 (ITIH1) is increased in human subjects with impaired glucose tolerance or diabetes and antibody neutralization of ITIH1 ameliorates systemic insulin resistance in mice." (PMID 34471136, 2021).
mental disorder (4 papers, 2018 to 2023). A disease that has its basis in the disruption of mental process. "Thus, there might be genetic risk factors, such as ITIH1, between the top-hit OA and the second-hit mental disorder." (PMID 36902448, 2023). "For example, for two mental disorder-related functional SNPs near genes PBRM1 and ITIH1 in the GWAS Catalog, PheWAS suggested they might be associated with lipoma." (PMID 29378629, 2018).
liver fibrosis (3 papers, 2012 to 2024). "ITIH1 levels were reduced in patients with liver fibrosis, and circulating ITIH1 mRNA levels were increased in rats with D-galactosamine-induced liver injury." (PMID 33076386, 2020).
lung carcinoma (3 papers, 2008 to 2019). "Earlier, Paris and coworkers revealed the roles of ITIH1 and ITIH3 in reducing the metastasis of lung cancer in mice while increasing cell attachment in vitro." (PMID 31481982, 2019). "Finally, ITIH1 and ITIH3 have been shown to increase cell attachment and to reduce the number of lung cancer metastases in mice." (PMID 18226209, 2008).
schizophrenia (3 papers, 2020 to 2024). A major psychotic disorder characterized by abnormalities in the perception or expression of reality. "Our findings are consistent with previous research indicating that ITIH1 polymorphisms are linked to an increased risk of schizophrenia and major depressive disorder, as well as cognitive dysfunction in psychotic disorders." (PMID 38898596, 2024). "Furthermore, our MR analysis confirmed the causal effects of increased ITIH1 levels on schizophrenia (OR = 1.105, p = 1.24 × 10−15) and major depressive disorder risk (OR = 1.029, p = 9.26 × 10−5)." (PMID 38898596, 2024).
Anxiety (2 papers, 2023 to 2025). Intense feelings of nervousness, tension, or panic often arise in response to interpersonal stresses. "A previous study found that deletion of the alpha 1 microglobulin/bikunin precursor, which is necessary for the functional complex of ITIH1 or ITIH3, increases anxiety behavior, suggesting the involvement of Itih3 in mood disorders." (PMID 36794261, 2023).
migraine (2 papers, 2024 to 2025). "ITIH1 (a protein) was significantly associated with the risk of migraine (OR = 1.044, 95% CI = 1.024–1.065, p = 1.08 × 10−5)." (PMID 40994718, 2025). "ITIH1 was significantly associated with the risk of migraine (OR = 1.044, 95% CI: 1.024–1.065, p = 1.08 × 10−5)." (PMID 40994718, 2025). "ITIH1 was significantly associated with the risk of any migraine (OR = 1.044, 95% CI = 1.024–1.065, p = 1.08 × 10−5) and migraine with visual disturbances." (PMID 38898596, 2024). "We also found compelling evidence that ITIH1 was associated with an increased risk of both overall migraine and migraine with visual disturbances." (PMID 38898596, 2024). "While ITIH4 was also associated with migraine risk, co‐localization analysis revealed that the causal variant (rs3755799) associated with both ITIH4 and any migraine is the same as the one linked to ITIH1 and any migraine." (PMID 38898596, 2024). "ITIH1 was significantly associated with an increased risk of any migraine (OR = 1.044, p = 1.08 × 10−5) and VD (OR = 1.067, p = 1.61 × 10−4)." (PMID 38898596, 2024). "We identified three tier 1 proteins (LRP11, ITIH1, and ADGRF5), whose genes have not been previously identified as causal genes for migraine in genetic studies." (PMID 38898596, 2024).
osteoarthritis (2 papers, 2022 to 2024). A noninflammatory degenerative joint disease occurring chiefly in older persons, characterized by degeneration of the articular cartilage, hypertrophy of bone at the margins and changes in the synovial membrane. "Although limited research exists on the association between ITIH1 and osteonecrosis, previous studies have linked ITIH1 with osteoarthritis." (PMID 39119575, 2024). "ITIH1 has previously been found to be elevated in patients with osteoarthritis." (PMID 36131342, 2022).
preeclampsia (2 papers, 2022 to 2025). Preeclampsia is a hypertensive disorder of pregnancy that is characterized by new-onset hypertension with proteinuria presenting after 20 weeks of gestation, and depending on mild or severe forms may initially present with severe headache, visual disturbances, and hyperreflexia. "A study investigating the maternal proteome in preeclampsia via LC–MS/MS approaches reported on 17 differentially expressed proteins in the serum, from which our study also identified VWF, PAPPA, FCN3, and ITIH1 as candidates associated with the mode of conception." (PMID 40974471, 2025).
Sepsis (2 papers, 2016 to 2025). Sepsis is defined as life-threatening organ dysfunction caused by a dysregulated host response to infection. "The decrease in ITIH1, ITIH2 and ITIH4, as compared to the increase in ITIH3, suggest a complex alteration in the protein balance of the IαI-family in sepsis." (PMID 40885913, 2025). "The decreased plasma levels of ITIH1, ITIH2 and ITIH4, as compared to the increased levels of ITIH3, suggest a complex alteration in the protein balance of the IαI-family in the pathophysiology of sepsis." (PMID 40885913, 2025).
type 1 diabetes (2 papers, 2016 to 2024). "These included associations for cis-pQTLs for inter-α trypsin inhibitor 1 (ITIH1) and type I diabetes and Siglec-9 linked with non-Hodgkin’s lymphoma." (PMID 39316441, 2024). "An ancestry-enriched cis-pQTL for ITIH1, a serum protease primarily expressed in the liver, was associated with type I diabetes." (PMID 39316441, 2024). "Although no mechanism has yet been proposed to directly connect ITIH1 with beta-cell-related functions, interleukin 17 receptor D is a candidate gene for type 1 diabetes and is overexpressed in response to proinflammatory cytokines." (PMID 27031336, 2016).
Arthritis (1 paper, 2023). Inflammation of a joint. "Roles for Itih1 and Itih2 have not been reported in the valve, but in arthritis, pathological degradation of cartilage has been attributed to ITI-HA complexes serving as substrates for ECM proteases—including ADAMTS-5, which has been described as a key player in myxomatous valve disease." (PMID 37623368, 2023).
atherosclerosis (1 paper, 2018). A disease characterized by the build-up of fatty material and calcium deposition in the arterial wall resulting in partial or complete occlusion of the arterial lumen. "Although there is evidence for a protective role of Timp3 in atherosclerosis, Itih1 and Itih2 have not yet been associated with plaque development." (PMID 29208753, 2018).
colorectal cancer (1 paper, 2023). A primary or metastatic malignant neoplasm that affects the colon or rectum. "Among the mutated genes in the adenomatous tissue samples involved in our study, PCDHGB4, AHRR, KIF4, LPAR6, NBPF1, and NCEH1 were already associated with colorectal cancer formation, while ANKRD30A, ITIH1, and KIAA0556 were related to other types of cancers." (PMID 36765865, 2023).
diffusive large B-cell lymphoma (1 paper, 2021). "For copy number variations (CNVs) of ITIH1, amplification was most frequently observed in esophagus cancer (1.65%), while deletion event occurred more often in diffusive large B-cell lymphoma (DLBC) (4.17%)." (PMID 33744857, 2021).
head and neck cancer (1 paper, 2008). A primary or metastatic malignant neoplasm affecting the head and neck. "In fact, in a survey on head and neck cancers, it has been proposed that the mapping site of ITIH1, 3 and 4 is a region which harbours several tumor-suppressor genes." (PMID 18226209, 2008).
head and neck squamous cell carcinoma (1 paper, 2021). A squamous cell carcinoma that arises from any of the following anatomic sites: lip and oral cavity, nasal cavity, paranasal sinuses, pharynx, larynx, and salivary glands. "We found that ITIH1 was negatively correlated with TMB of CHOL, head and neck squamous cell carcinoma (HNSC), LUAD, PAAD, rectum adenocarcinoma (READ), STAD, and Thymoma (THYM), but positively correlated with that of Brain lower grade glioma (LGG)." (PMID 33744857, 2021).
knee osteoarthritis (1 paper, 2024). "Proteomic analysis revealed significantly higher levels of ITIH1 in knee osteoarthritis patients than in healthy controls." (PMID 39119575, 2024). "Another study indicates that ITIH1 may enhance the ability to predict the incidence of knee osteoarthritis in clinical practice." (PMID 39119575, 2024).
macular degeneration (1 paper, 2024). Loss of vision in the central portion of the retina (macula), secondary to retinal degeneration. "In addition, we observed CFHR3 to be associated with macular degeneration, and OMG and ITIH1 to be associated with height." (PMID 38540773, 2024).
melanoma (1 paper, 2021). A malignant, usually aggressive tumor composed of atypical, neoplastic melanocytes. "Melanoma demonstrated the highest frequency of ITIH1 mutation (8.33%), followed by uterine cancer (5.86%)." (PMID 33744857, 2021).
osteonecrosis (1 paper, 2024). A none disease characterized by death of bone tissue due to a lack of blood supply. "This comprehensive MR study identifies 71 plasma proteins associated with osteonecrosis, with HEBP1, ITIH1, SMOC1, and CREG1 showing potential as biomarkers of osteonecrosis." (PMID 39119575, 2024). "Additionally, we also found a suggestive association of inter-alpha trypsin inhibitor heavy chain 1 (ITIH1), secreted modular calcium-binding protein 1 (SMOC1), and cellular repressor of E1A-stimulated genes 1 (CREG1) proteins with osteonecrosis risk." (PMID 39119575, 2024).
Pheochromocytoma and Paraganglioma (1 paper, 2021). "A negative correlation between ITIH1 expression and MSI was seen in PAAD, Pheochromocytoma and Paraganglioma (PCPG), and STAD, whereas a positive correlation was found for Prostate adenocarcinoma (PRAD)." (PMID 33744857, 2021).
rheumatoid arthritis (1 paper, 2024). A chronic, systemic autoimmune disorder characterized by inflammation in the synovial membranes and articular surfaces. "We discovered that higher plasma MAPK3 levels could reduce the risk of rheumatoid arthritis (RA), while higher plasma ITIH1 levels might increase the risk of bipolar and reduce the risk of chronic ischemic heart disease." (PMID 38540773, 2024).
sarcopenia (1 paper, 2026). Progressive decline in muscle mass due to aging which results in decreased functional capacity of muscles. "We identified seven robust protein signatures (LRG1, CST3, TIMP1, C2, ITIH1, AMBP and LYZ) that showed consistent significant associations with sarcopenia components in both cohorts." (PMID 41782349, 2026).
Shock (1 paper, 2025). The state in which profound and widespread reduction of effective tissue perfusion leads first to reversible, and then if prolonged, to irreversible cellular injury. "Our study supports the findings regarding ITIH2 and ITIH3, but we observed a significant decrease in ITIH1 plasma levels in patients with septic shock while AMBP remained unchanged." (PMID 40885913, 2025).
stomach adenocarcinoma (1 paper, 2021). "For example, ITIH1 and ITIH4 were more highly expressed in stomach adenocarcinoma (STAD) and kidney renal clear cell carcinoma (KIRC) as compared with the normal tissues." (PMID 33744857, 2021).
thyrotoxicosis (1 paper, 2022). A hypermetabolic syndrome caused by the elevation of thyroid hormone levels in the serum. "In the present study, Itih1, Itih2, Itih3, and Itih4 were downregulated in thyrotoxicosis mice, which also reflected the decline of defense and protective capability." (PMID 35720307, 2022).
type 2 diabetes (1 paper, 2020). "For example, ITIH1 antibodies can be developed for the treatment of type 2 diabetes." (PMID 32576930, 2020).